AP3M2 (adaptor related protein complex 3 subunit mu 2)
Description:
Part of the AP-3 complex, an adaptor-related complex which is not clathrin-associated. The complex is associated with the Golgi region as well as more peripheral structures. It facilitates the budding of vesicles from the Golgi membrane and may be directly involved in trafficking to lysosomes. In concert with the BLOC-1 complex, AP-3 is required to target cargos into vesicles assembled at cell bodies for delivery into neurites and nerve terminals.
Synonyms: CLA20; AP47B; P47B
Tractability: Antibody: UniProt places it where antibodies can reach, with medium confidence. PROTAC: ubiquitination databases record sites on it; its protein half-life has been measured.
Gene: Protein-coding gene on chromosome 8 (42,152,946 to 42,171,673, forward strand). Ensembl gene ENSG00000070718.
Subcellular location: Golgi apparatus; Cytoplasmic vesicle membrane
Gene Ontology:
Molecular function: clathrin adaptor activity; AP-3 adaptor complex binding
Biological process: anterograde axonal transport; anterograde synaptic vesicle transport; clathrin-coated vesicle cargo loading, AP-3-mediated; endocytosis; Golgi to vacuole transport; synaptic vesicle coating; synaptic vesicle recycling; intracellular protein transport; synaptic vesicle endocytosis; vesicle-mediated transport
Cellular component: AP-3 adaptor complex; AP-type membrane coat adaptor complex; early endosome; axon cytoplasm; clathrin adaptor complex; cytoplasmic vesicle membrane; GABA-ergic synapse; glutamatergic synapse; Golgi apparatus; synaptic vesicle
Genetic constraint (gnomAD): Loss-of-function variants: 26 observed, 42.02 expected, observed/expected ratio (o/e) 0.62, 90% interval 0.45 to 0.86. The upper end of that interval is the gene's LOEUF score, 0.86, which puts it in group 3 of 6, group 1 being the genes least tolerant of losing a copy. Missense variants: 424 observed, 542.66 expected, observed/expected ratio (o/e) 0.78, 90% interval 0.72 to 0.85. Synonymous variants: 193 observed, 195.89 expected, observed/expected ratio (o/e) 0.99, 90% interval 0.88 to 1.11.
Homologues: Orthologues: chimpanzee AP3M2 (100% identical), dog AP3M2 (99% identical), macaque AP3M2 (99% identical), guinea pig AP3M2 (99% identical), pig AP3M2 (99% identical), rabbit AP3M2 (99% identical), mouse Ap3m2 (98% identical), rat Ap3m2 (98% identical), tropical clawed frog ap3m2 (92% identical), zebrafish ap3m2 (91% identical), Drosophila melanogaster cm (70% identical). Paralogues in human: AP3M1 (84% identical), AP1M2 (30% identical), AP1M1 (28% identical), AP2M1 (26% identical), AP4M1 (20% identical), STON2 (17% identical), STON1 (16% identical).
Diseases named in the same sentence as AP3M2 in open-access papers:
AP3M2 is named in the same sentence as 22 diseases in open-access papers, as found by Europe PMC text mining. Sharing a sentence is not in itself a finding about the gene and the disease. The quoted sentences say what the papers report.
colon cancer (2 papers, 2024 to 2025). "It was observed that a higher AP3M2 expression level was significantly associated with unfavorable Overall Survival (OS) in colon cancer (p-value = 0.016, HR: 2), indicating a two-fold higher risk." (PMID 38177168, 2024). "In our study, AP3M2 was found to be associated with oxaliplatin response in colon cancer." (PMID 38177168, 2024). "Notably, a high level of AP3M2 might be associated with poor treatment response among colon cancer patients receiving oxaliplatin therapy." (PMID 38177168, 2024). "There were statistical significances in the AP3M2 expression levels between pathologic N0 (median 8.33), N1(median 7.28), N2 (median 9.19), and normal (median 3.94) in colon cancer." (PMID 38177168, 2024). "At the same time, AP3M2 seems can be a biomarker between colon cancer and colonic adenomas, liver metastasis, lung metastasis, colonic polyp." (PMID 38177168, 2024). "Further research is warranted to investigate how AP3M2 affects drug effectiveness and colon cancer prognosis." (PMID 38177168, 2024). "The expression level of AP3M2 in stage 1 to 4 colon cancer tissues was higher than that in adjacent normal tissue (stage 1 vs. stage 2 vs. stage 3 vs. stage 4: 7.95 vs. 8.51 vs. 8.42 vs. 7.40)." (PMID 38177168, 2024). "The expression levels of AP3M2 in colon cancer patients of different groups are similar to the expression level of rectal cancer, but they have no significantly relevant with age and gender." (PMID 38177168, 2024). "In order to reveal the relationship between AP3M2 and immune regulation in colon cancer, we then explore the gene and immune cell infiltration through TIMER database." (PMID 38177168, 2024). "AP3M2 might be the primary biomarker for oxaliplatin in colon cancer and an acquired resistance biomarker for oxaliplatin and 5-fu." (PMID 38177168, 2024). "In addition, there were statistical significances in the AP3M2 expression levels between N1 and N2 in colon cancer (p-value < 0.05)." (PMID 38177168, 2024). "The expression of AP3M2 in colon cancer samples and adjacent normal tissues." (PMID 38177168, 2024). "AP3M2 could potentially predict chemotherapy effectiveness and prognosis for colon cancer patients." (PMID 38177168, 2024). "AP3M2 could predict chemotherapy effectiveness and prognosis for colon cancer patients." (PMID 38177168, 2024). "The relationship between AP3M2 and ABCG2 was positive in colon cancer (r = 0.12) and rectal cancer (r = 0.18)." (PMID 38177168, 2024). "Based on the rocplot.plot analysis, in colon cancer patients, the expression level of AP3M2 was found to be higher in non-responders compared to responders who received oxaliplatin (AUC = 0.693, p-value = 2e−03)." (PMID 38177168, 2024). "Based on these results, the expression profile of AP3M2 changed as HCT‐116 cells become more aggressive in vitro—suggesting that AP3M2 may be involved in extracellular matrix remodelling and cell adhesion molecule regulation—for colon cancer invasion and metastasis." (PMID 40008534, 2025).
breast carcinoma (1 paper, 2010). "The amplification of the MYST3 and AP3M2 genes was already described like recurrent amplicons associated with reduced survival duration in breast cancer." (PMID 20877358, 2010).
colon adenocarcinoma (1 paper, 2024). "This contradicts our conclusion that the overexpression of AP3M2 is positively associated with dendritic cell infiltration in colon adenocarcinoma." (PMID 38177168, 2024). "Higher AP3M2 expression levels were associated with longer overall survival in colon adenocarcinoma." (PMID 38177168, 2024). "Meanwhile, it plays an antioncogene role in Glioblastoma multiforme, Kidney Chromophobe and Thyroid carcinoma.In our study, enhanced expression of AP3M2 predicts poor prognosis in patients with colon adenocarcinoma, but not rectal adenocarcinoma." (PMID 38177168, 2024).
colorectal adenocarcinoma (1 paper, 2024). The most common type of colorectal carcinoma. "The expression levels and prognostic role of AP3M2 in colorectal adenocarcinoma (CRAC) have yet to be fully unveiled." (PMID 38177168, 2024). "Our study comprehensively analyzed the role of AP3M2 in colorectal adenocarcinoma, incorporating data from both TCGA and GEO." (PMID 38177168, 2024). "Moreover, AP3M2 overexpression in colorectal adenocarcinoma can also increase the amount of immunosuppressive cells, such as regulatory T cells (Treg) and medullary inhibitory cells, to evade immune surveillance, the numbers of these immunosuppressive cells are closely related to a poor prognosis." (PMID 38177168, 2024). "In our study, AP3M2 was found to be positively related to PD-L1(CD274), hypoxic response, NF-kB pathway, and NK cell infiltration in colorectal adenocarcinoma." (PMID 38177168, 2024).
colorectal adenoma (1 paper, 2024). An adenoma that arises from the colon or rectum. "We found AP3M2 is a cancer gene, which can be used to distinguish between colorectal cancer and colorectal adenomas, liver metastasis, lung metastasis, colorectal polyp." (PMID 38177168, 2024).
colorectal cancer (1 paper, 2024). A primary or metastatic malignant neoplasm that affects the colon or rectum. "In this study, we explored the role of AP3M2 in colorectal cancer by using an extensive bioinformatics data mining process to determine the expression of AP3M2 in various cancers." (PMID 38177168, 2024). "Our study comprehensively investigated the clinical significance of AP3M2 in colorectal cancer through an extensive bioinformatics data mining process (TCGA, GEO, GEPIA, Timer, Ualcan, ROCPLOT, and David), followed by experimental validation." (PMID 38177168, 2024). "Therefore, we speculate that AP3M2 plays a possible role in colorectal cancer immunotherapy." (PMID 38177168, 2024). "Furthermore, AP3M2 might not be some clinic factor such as different stages, age groups, or gender of colorectal cancer." (PMID 38177168, 2024).
rectal cancer (1 paper, 2024). A primary or metastatic malignant neoplasm that affects the rectum. "This explains the different prognosis of AP3M2 in colon and rectal cancer." (PMID 38177168, 2024). "More notably, AP3M2 is independent of Immune Regulation in rectal cancer, which explains the different prognosis manifestation in the rectum instead." (PMID 38177168, 2024).
rectal tumor (1 paper, 2024). "In our study, FOXP3(r = 0.179), CD72(r = 0.155), RUNX1(r = 0.327), LAG3(r = 0.194), CTLA4(r = 0.236) have a positive correlation with AP3M2 in Colon Neoplasm, but no irrelevancy in rectal tumor." (PMID 38177168, 2024).
cancer (2 papers, 2024). A tumor composed of atypical neoplastic, often pleomorphic cells that invade other tissues. "According to TCGA data from the TIMER database, the transcription level of AP3M2 across various cancer types showed statistical significance (p-value < 0.01)." (PMID 38177168, 2024).
tumor (1 paper, 2024). "AP3M2 might inhibit tumor growth via influencing tumor-infiltrating immune cells in the context of Tumor microenvironment." (PMID 38177168, 2024). "Moreover, AP3M2 might inhibit tumor growth by influencing tumor-infiltrating immune cells (TICs) in the context of the tumor microenvironment (TME)." (PMID 38177168, 2024). "The level of AP3M2 expression was higher in the tumor group compared to the normal group (p < 0.05)." (PMID 38177168, 2024).
AP3M2 also shares sentences with these, for which no sentence is quoted: Breast invasive carcinoma (1 paper); cholangiocarcinoma (1); colonic adenomas (1); colonic polyp (1); colorectal polyp (1); Esophageal carcinoma (1); Glioblastoma multiforme (1); head and neck squamous cell carcinoma (1); Kidney Chromophobe (1); Lung squamous cell carcinoma (1); rectal adenocarcinoma (1); Stomach adenocarcinoma (1).